RNU6-1046P (RNA, U6 small nuclear 1046, pseudogene)
Gene: Small nuclear RNA gene on chromosome 14 (23,259,460 to 23,259,566, reverse strand). Ensembl gene ENSG00000252347.
Homologues: Orthologues: chimpanzee U6 (99% identical), macaque U6 (94% identical), guinea pig U6 (79% identical), dog U6 (66% identical), mouse Gm55959 (57% identical). Paralogues in human: RNU6-797P (82% identical), RNU6-196P (81% identical), RNU6-639P (80% identical), RNU6-1145P (79% identical), RNU6-115P (79% identical), RNU6-1209P (79% identical), RNU6-38P (79% identical), RNU6-533P (79% identical), RNU6-59P (79% identical), RNU6-605P (79% identical), RNU6-183P (79% identical), RNU6-393P (79% identical), and 1285 more.